IL22 (interleukin 22)
Diseases named in the same sentence as IL22 in open-access papers (continued):
Sharing a sentence is not in itself a finding about the gene and the disease.
colitis (continued). "A recent report showed that the receptor-interacting protein kinase 3 promotes intestinal tissue repair after DSS colitis via induction of IL-22 expression in a IL-23 and IL-1β dependent manner." (PMID 31816903, 2019). "We have demonstrated that TP5 protected colitis by producing IL-22 through RORγt/IL-22 signaling pathway, although how RORγt is induced by TP5 is not known." (PMID 31695782, 2019). "Exogenous IL-22 also mitigates Citrobacter rodentium infection mediated colitis in mice with depletion of CX3CR1+ mononuclear phagocytes." (PMID 31816903, 2019). "The expression of IL-22 mRNA increased in both colon and mesenteric lymph nodes in mice with colitis." (PMID 30956679, 2019). "IL-23-responsive IL-22 was also shown to relieve colon inflammation in murine colitis induced with dextran sodium sulfate or Citrobacter Rodentium67 and ILC3-deficient mice generated scant IL-22 to enhance sensitivity to Citrobacter Rodentium68." (PMID 30962426, 2019). "Ficz, which is a ligand of Ahr capable of inducing IL-22 expression, was reported to improve the colitis of the CD45RB model as well as acute CD model induced by intrarectal administration of trinitrobenzene sulfonic acid (TNBS)." (PMID 29075900, 2018). "This review article discusses how IL-22 regulates colitis, how beneficial versus deleterious effects of IL-22 is determined, and why IL-22 represents a promising target for IBD therapy." (PMID 29075900, 2018). "Mice devoid of IL-22 which enhances the production of antimicrobials by IECs also show high sensitivity to DSS colitis, indicating IL-22 from T cells is protective against intestinal inflammation." (PMID 29619131, 2018). "CD177+ neutrophils produce IL-22 for improving colitis and this neutrophil subset increases in the peripheral blood and inflamed intestine of UC and CD patients." (PMID 29075900, 2018). "Recently, neutrophils have been shown to be a main source of secreted IL-22 in the colon during C. rodentium infection and colitis." (PMID 30365535, 2018). "T cells and type 3 innate lymphoid cells produce IL-22 during colitis in response to IL-23 and IL-1β." (PMID 29967613, 2018). "IL-33 is a well-known regulator of mucin responses in multiple inflammatory settings, but our colitis model largely found IL-13- and IL-22-dependent signaling." (PMID 30518915, 2018). "Immune cell-produced regulatory factors such as IL-10 and IL-22 promote mucous production and protect from colitis." (PMID 29454391, 2018). "Therapeutic benefit of tryptophan on experimental colitis through activation of the IL-22 pathway has also been demonstrated." (PMID 29075900, 2018). "It has been demonstrated that CARD9 promotes recovery from colitis through activation of the IL-22 pathway." (PMID 30008619, 2018). "IL-23R-mediated signaling stimulates epithelial cells to produce RegIIIβ, which then recruits IL-22-producing neutrophils capable of improving colitis." (PMID 29075900, 2018). "RegIIIβ is, at first, produced by epithelial cells through IL-23 receptor signaling, and the epithelial-derived RegIIIβ then recruits IL-22-producing neutrophils that contribute for the improvement of colitis." (PMID 29075900, 2018). "In a murine TNBS colitis model, an AhR antagonist induced more severe colitis by suppressing synthesis of IL-22." (PMID 29910812, 2018). "In mouse DSS-induced colitis, IL-22 delivery attenuated disease, while IL-22−/− mice suffered greater weight loss compared with wild-type mice." (PMID 28302598, 2017). "Accordingly, treatment of Ahr ligand ameliorated the pathology of several mouse colitis models, including 2,4,6-trinitrobenzenesulfonic acid (TNBS)-, DSS-, and T cell transfer-induced colitis, in which IL-22 is required." (PMID 29354125, 2017). "IL-22 is a critical mediator of gut barrier defense against bacterial pathogens and underpins therapeutic helminth infection in human colitis." (PMID 28330898, 2017).
colitis (continued). "Yet, active colitis and colitis in remission upon conventional therapy also featured elevated IL-22 expression levels compared to healthy controls." (PMID 27152519, 2016). "Previous studies have demonstrated a reduction in the abundance of Turicibacter in the gastrointestinal tracts of mice with colitis (DSS-induced and IL-22-deficient mice)." (PMID 27863401, 2016). "Wild-type mice infected with H. diminuta were protected from colitis, as were infected IL-22-/- mice and the latter to a degree that they were almost indistinguishable from control, non-DNBS treated mice." (PMID 27055194, 2016). "Moreover, in a colitis-associated colon cancer model, IL-22BP-deficient mice showed accelerated tumor development and an increase in quantity and size of tumors compared to wild type control mice, suggesting an important role for IL-22 in colitis-associated CRC." (PMID 28536374, 2016). "Although IL-22 is considered to prevent colitis development, it also promotes pathogen colonization by suppressing related commensal bacteria in mice." (PMID 27424033, 2016). "For example, in the gastrointestinal tract of mice with experimental colitis, neutrophils become activated and are subsequently capable of expressing IL-22." (PMID 26793707, 2015). "During colitis, IL-22 is responsible for regulating mucin production from goblet cells, which constitutes the protective mucous layer that lines the intestinal epithelium." (PMID 26793707, 2015). "T cells were cultured under IL-22-promoting conditions, purified for IL-22 reporter expression, and transferred into Rag1−/− recipients to generate colitis." (PMID 26834739, 2015). "Modulating the balance between Treg and Th17 cells by IL-22 can also reduce the pathological degree in experimental colitis." (PMID 25889203, 2015). "In a mouse model of colitis, Zindlet al. described the role of IL-22-producingneutrophils in intestinal protection." (PMID 26108096, 2015). "Contrary to these findings in human IBD, studies on mouse models of colitis suggested the protective role of IL-22 in the intestine." (PMID 26199463, 2015). "Having analyzed plasticity of IL-22 expressers generated in vitro, we next examined IL-22 expressers generated in a pathological setting in vivo by colitis induction." (PMID 26834739, 2015). "IL-22 presented high quantities in the blood of the patients with Crohn's disease, and IL-22 mRNA expression was elevated predominantly in mouse colitis model." (PMID 24899787, 2014). "Mice with colitis infected with H. polygyrus had higher concentrations of IL-6, IL-12p70, IL-10, IL-22 and MCP-1 but lower amounts of IL-17A (from 5.4 pg/mL to 3.2 pg/mL) at 6 DPI." (PMID 24167594, 2013). "DSS colitis in Rag1−/− mice induces colonic LTi-like cells to produce IL-22: the percentage of LTi-like cells producing IL-22 increases from ∼13% in healthy (control) conditions to ∼37% in inflammatory (DSS) conditions." (PMID 23750260, 2013). "The leukocyte infiltration into the mucosa and submucosa of the small intestine of mice with colitis at 6 DPI was associated with increased concentration of IL-6, IL-12p70, IL-10, IL-22 MCP-1 and TNF-α, IL-1β, MPO but lower concentration of IL-17A." (PMID 24167594, 2013). "In contrast with these protective properties, IL-22 has been shown to promote colitis in some settings." (PMID 23405904, 2013). "Similar outcomes have been obtained from a colitis mouse model, indicating that highly elevated IL-22 expression was an inflammation driver in either a direct or indirect manner." (PMID 23379788, 2013). "Blockade of IL-22 by using its neutralizing antibody reversed the therapeutic effect of 6-formylindolo (3, 2-b) carbazole on the trinitrobenzenesulfonic acid-induced colitis in mice." (PMID 23956763, 2013). "STAT3 activation in murine colitis is dependent on IL-22, which is secreted by cells of the innate immune system." (PMID 22675454, 2012).
colitis (continued). "Last, based on the important role demonstrated for IL-22 in colitis experiments in Opn−/− mice, we analyzed the effect of OPN gene variants on IL-22 serum levels." (PMID 22242114, 2011). "Blockade of IL-22 with a neutralizing antibody reversed the therapeutic effect of Ficz in mice with TNBS-colitis, thus indicating that induction of IL-22 is one of the major mechanisms by which AhR signals control pathogenic responses in the gut." (PMID 22082127, 2011). "By contrast, the very mechanisms that confer resistance to colitis in Stat3 proficient epithelium also promote tumourigenesis, including IL22-dependent induction of tumour-promoting inducible nitric-oxide synthase." (PMID 20478049, 2010). "We also assessed the expression of genes encoding colitis-associated cytokines that influence susceptibility to C. rodentium infection, including IL-17A and IL17F, IL-22, and IL-23." (PMID 20485566, 2010). "Accordingly, experimental delivery of IL22 to mice with DSS-induced colitis reduced inflammatory infiltrates and promoted the mucosal healing response by goblet cells." (PMID 20478049, 2010). "IL-22 is increased in the mucosa of patients with IBD157, and mice lacking IL-22 are more susceptible to colitis." (PMID 41459728, 2026). "Similarly, administration of FICZ, an AhR agonist, promoted IL‐22 secretion and significantly ameliorated chemically induced colitis, while AhR antagonists worsened disease severity." (PMID 41583118, 2026). "Furthermore, activated AhR enhances the expression of IL-22, which helps suppress intestinal inflammation in mice with colitis." (PMID 41031160, 2025). "In contrast, blocking IL-22 alleviated colitis by inhibiting epithelial ER stress." (PMID 40243444, 2025). "Because all our findings presented above are based on a DSS or AOM/DSS inflammation-associated model (a tumor prevention model), blocking immune cell infiltration through TH17 cells or their cytokines (IL-17 and/or IL-22) markedly reduces inflammation-induced colitis and tumor development." (PMID 40749055, 2025). "In contrast, a previous study found that IL-22 promotes neutrophil recruitment to the colon after colitis induction, indicating that the effect of IL-22 on neutrophils may be specific to different tissue microenvironments." (PMID 41467015, 2025). "In a dextran sulfate sodium (DSS)-induced colitis mouse model, SAA3 deficiency exacerbated the disease condition by increasing the expression of pro-inflammatory cytokines and decreasing the expression of IL-22-producing neutrophils." (PMID 40429677, 2025). "IL-22 signaling was crucial for the induction of hemopexin in the colon, as Il22ra1-/- mice exhibited limited hemopexin induction and more severe colitis, which could be reversed by recombinant hemopexin administration." (PMID 40791589, 2025). "However, future studies using an IL-22 receptor (IL-22R)–deficient mouse model would be valuable in further elucidating the specific role of IL-22 in colitis protection." (PMID 40749055, 2025). "One potential mechanism is through the stimulation of mucus production via the cytokine IL-22, which may help alleviate colitis symptoms and improve gut health." (PMID 40430744, 2025). "Supplementing NEC model mice with IL22 can effectively alleviate colitis." (PMID 38814387, 2025). "Finally, CARD9 is involved in the recovery from colitis through the production of IL-22 and other antimicrobial peptides." (PMID 40002718, 2025). "In addition, Indole-3-methanol, a derivative of indole present in cruciferous vegetables, has been shown to alleviate colitis in mice by upregulating interleukin-22 (IL-22), a cytokine that strengthens epithelial immunity and modulates intestinal inflammation." (PMID 40771692, 2025). "IL-22–dependent pathophysiology in A20ZF7 mice also appears distinct from that seen in Treg- and IL-10–deficient mice in that A20ZF7 mice develop proximal enteritis, while the latter models predominantly develop colitis." (PMID 40892518, 2025).
colitis (continued). "Furthermore, indole-3-carbinol has been reported to alleviate symptoms through stimulating IL-22 expression in a murine colitis model, which resulted in the generation of anti-inflammatory butyrate by the intestinal microbiome." (PMID 40730483, 2025). "Moreover, in the absence of adaptive immunity, ILC3s adopted an inflammatory phenotype and produced higher amounts of IL-17, IL-22, GM-CSF, and IFNγ, which further exacerbated colitis." (PMID 40498001, 2025). "It has been shown that IL‐22 originating from memory/effector T cells induces pathogenicity, whereas IL‐22 produced by naïve T cells had a protective role in the T‐cell transfer colitis model." (PMID 38363052, 2024). "It has also been shown that IL‐22 can exacerbate colitis in some murine models." (PMID 38363052, 2024). "In summary, our findings indicate that certain strains of Akk may mitigate colitis through the promotion of RA synthesis and IL-22 secretion, underscoring the potential efficacy of Akk as a therapeutic intervention for the management of UC." (PMID 39734222, 2024). "This indicates that memory/effector T‐cell‐derived IL‐22 might be involved in the pathogenicity of the colitis model used in this study." (PMID 38363052, 2024). "Gut: Supplementation with L. acidophilus, or its metabolite ILA, attenuates inflammation and restores IL-22 levels through AhR signaling in mice.Similar results were observed in a mice model of DSS-induced colitis supplemented with two strains of ILA-producing B. bifidum." (PMID 38675450, 2024). "CARD9 promotes recovery from colitis by promoting AhR ligands and IL-22 production." (PMID 39767818, 2024). "Additionally, activation of AhR by I3C has been shown to reduce TNBS- or DSS-induced colitis and alleviate microbial dysbiosis resulting from colitis, and this effect occurs in an IL-22-dependent manner." (PMID 39767818, 2024). "To study a role of IL-22-mediated signaling axis during intestinal inflammation, we generated a set of small protein blockers of IL-22R1 and verified their inhibitory potential on murine model of colitis." (PMID 39354587, 2024). "In fact, studies have shown that the increased level of IL-22 induced by AhR agonists, along with the reduction in IFNγ in mononuclear cells of lamina propria, determines healing from chemical and T cell transfer-model-induced colitis." (PMID 38543132, 2024). "The seemingly conflicting roles of IL-23 in colitis models could be attributed, in part, to the enhancement of barrier function and wound healing through the IL-23‒IL-22 pathway." (PMID 39379604, 2024). "Subsequently, this leads to the secretion of IL-22 by ILC3s and mitigates colitis." (PMID 39734222, 2024). "However, future studies blocking IL-22 during colitis in both male and female mice and investigating how this impacts B. acidifaciens abundance can provide more definitive proof this cytokine impacts this species specifically." (PMID 39229279, 2024). "Exogenous IL-22 accelerates recovery from acute DSS colitis in Ire1αΔRorc mice." (PMID 38722686, 2024). "Meanwhile, IL-22 serves as a pivotal mediator of host mucosal immunity, possessing functions such as apoptosis inhibition, alleviation of intestinal inflammation, and tissue injury restoration in colitis." (PMID 39211040, 2024). "The focus of the current report, after identifying ILC3s/T cells as a major source of IL-22 during colitis, was to target AhR deletion in these specific cell types, assess IL-22 production, and determine how this impacted Bacteroides abundance in the gut during colitis." (PMID 39229279, 2024). "IL‐22 also had a detrimental effect in the T‐cell transfer model of experimental colitis." (PMID 38363052, 2024). "During colitis, the release of several proinflammatory mediators, such as IL-6, IL-18, IL-22, and RELMβ, has been shown to enhance the intestinal epithelial cells proliferation, induce the release of antimicrobial peptides and anti-inflammatory mediators and promote the mucosa wound healing." (PMID 39684467, 2024).
colitis (continued). "The increase in CD8+ T cells in the blood and the increase in effector CD8+ T cells in the mLN in non-challenged mice and in mice with acute DSS colitis, respectively, were associated with elevated level of IL22 in the same organs." (PMID 39076972, 2024). "This Rag1−/− model has been employed to study the role of IL22 in colitis." (PMID 38363052, 2024). "This is consistent with our previous research results that IAA released by indole acetylated starch in colon, and the remission effect on colitis may be closely related to the activation of the AHR/IL-22 pathway." (PMID 39458442, 2024). "In contrast, B. fragilis strain ZY-312 can alleviate colitis in an IL-22-dependent manner." (PMID 39734222, 2024). "Collectively, these data showed that I3C treatment during colitis was able to alter expression of IL-22 and its receptor in a cell-specific manner, with the most notable change being overall IL-22 production regulated to the cluster most prominently identified as T cells or T cell-like." (PMID 39229279, 2024). "Besides elevating the LC3-II/LC3-I ratio, ATG5 and Beclin-1 levels and decreasing P62 level, the ANI/NEO combination decreased the expression of several inflammatory cytokines (INF-γ, TNF-α, IL-6, and IL-22) in colon tissue from mice with DSS-induced colitis." (PMID 38354108, 2024). "A comprehensive metabolomic and microbiota profiling revealed an important correlation between indole-3-carbinol, glucobrassicin metabolite, Roseburia spp., a butyrate-producing bacteria, and IL22, an anti-inflammatory cytokine, for gut protection against colitis." (PMID 38779039, 2024). "IL‐22 has been shown to be protective in a colitis model applied in mice." (PMID 38363052, 2024). "In our previous report, we showed a natural product in cruciferous vegetables and ligand of the aryl hydrocarbon receptor (AhR), indole-3-carbinol (I3C), was able to reduce colitis-induced disease severity and microbial dysbiosis in an interleukin-22 (IL-22) dependent manner." (PMID 39229279, 2024). "Furthermore, the novel Akk strain Am06 isolated from breast milk shows consistent RA synthesis and IL-22 induction abilities, like the reference strain, and thereby effectively protects against experimental colitis." (PMID 39734222, 2024). "In our previous publication, we noted that neutralizing IL-22 during TNBS colitis induction in female mice led to significant increases of B. acidifaciens which suggested this cytokine was important in regulating abundance of this species in the gut microbiome." (PMID 39229279, 2024). "As hypothesized, the beneficial impact of Akk supplementation on wild-type mice's colitis was completely abolished in IL-22−/− mice." (PMID 39734222, 2024). "In addition, given results showing B. acidifaciens can induce a colitis-like phenotype in female GF mice, effect of this species on AhR, ILC3s, and IL-22 specifically in this model should be explored." (PMID 39229279, 2024). "Importantly, FBTP can reshape the gut microbiome and promote the conversion of tryptophan to indole-3-acetic acid by the microbes, which subsequently leads to colitis protection by enhancing the expression of IL-22 and tight-linking proteins in the colon." (PMID 38549666, 2024). "Besides, 3-MA increased the proinflammatory factors levels (TNF-α, IL-6, IFN-γ, IL-22) in ANI/NEO-treated mice with DSS-induced colitis." (PMID 38354108, 2024). "Thus, we concluded that B3galt5 plays a significant role in facilitating IL-22-mediated protection from colitis development." (PMID 38733584, 2024). "The genus Blastocystis was the most prevalent genus in this study and is known to confer beneficial effects on the host immune system, such as stimulating mucus production through the cytokine IL-22, which improves intestinal health and alleviates colitis symptoms." (PMID 39202752, 2024).